RAB3GAP2 (RAB3 GTPase activating non-catalytic protein subunit 2)
Description:
Regulatory subunit of the Rab3 GTPase-activating (Rab3GAP) complex composed of RAB3GAP1 and RAB3GAP2, which accelerates the otherwise slow GTP hydrolysis catalyzed by Rab proteins. The complex has GTPase-activating protein (GAP) activity towards various Rab3 subfamily members (RAB3A, RAB3B, RAB3C and RAB3D), RAB5A and RAB43, and has guanine nucleotide exchange factor (GEF) activity towards RAB18. The Rab3GAP complex acts as a GEF for RAB18 by promoting GDP release from RAB18 and the conversion of inactive RAB18-GDP to the active form RAB18-GTP. Recruits and stabilizes RAB18 at the cis-Golgi membrane in human fibroblasts where RAB18 is most likely activated. Also involved in RAB18 recruitment at the endoplasmic reticulum (ER) membrane where it maintains proper ER structure. Required for normal eye and brain development (By similarity). May participate in neurodevelopmental processes such as cell proliferation, migration and differentiation before synapse formation, and non-synaptic vesicular release of neurotransmitters (By similarity).
Synonyms: Rab3-GAP150; KIAA0839; DKFZP434D245; SPG69; MARTS1; RAB3GAP150; WARBM2; p150
Tractability: Antibody: its Gene Ontology location is reachable by antibodies, with high confidence. PROTAC: ubiquitination databases record sites on it; its protein half-life has been measured.
Gene: Protein-coding gene on chromosome 1 (220,148,293 to 220,272,529, reverse strand). Ensembl gene ENSG00000118873.
Subcellular location: Cytoplasm; Endoplasmic reticulum
Subcellular location (Human Protein Atlas): Cytosol; Plasma membrane
Pathways (Reactome):
Vesicle-mediated transport: COPI-independent Golgi-to-ER retrograde traffic; RAB GEFs exchange GTP for GDP on RABs
Gene Ontology:
Molecular function: guanyl-nucleotide exchange factor activity; protein binding; small GTPase binding; enzyme activator activity; enzyme regulator activity; GTPase activator activity
Biological process: establishment of protein localization to endoplasmic reticulum membrane; positive regulation of autophagosome assembly; positive regulation of endoplasmic reticulum tubular network organization; intracellular protein transport; macroautophagy; positive regulation of protein lipidation; synaptic signaling
Cellular component: cytosol; GTPase complex; protein-containing complex; autophagosome; cytoplasm; endoplasmic reticulum membrane; plasma membrane; presynaptic membrane; endoplasmic reticulum
Genetic constraint (gnomAD): Loss-of-function variants: 72 observed, 163.88 expected, observed/expected ratio (o/e) 0.44, 90% interval 0.36 to 0.54. The upper end of that interval is the gene's LOEUF score, 0.54, which puts it in group 2 of 6, group 1 being the genes least tolerant of losing a copy. Missense variants: 1,367 observed, 1,576 expected, observed/expected ratio (o/e) 0.87, 90% interval 0.83 to 0.91. Synonymous variants: 519 observed, 561.07 expected, observed/expected ratio (o/e) 0.93, 90% interval 0.86 to 1.
Gene-disease validity (ClinGen):
ClinGen rates the evidence that RAB3GAP2 causes each of these diseases.
Warburg micro syndrome (autosomal recessive): Definitive. Micro syndrome is an autosomal recessive disorder caracterised by ocular and neurodevelopmental defects and by microgenitalia.
Homologues: Orthologues: chimpanzee RAB3GAP2 (99% identical), macaque RAB3GAP2 (99% identical), dog RAB3GAP2 (92% identical), pig RAB3GAP2 (89% identical), mouse Rab3gap2 (89% identical), rat Rab3gap2 (88% identical), rabbit RAB3GAP2 (87% identical), guinea pig RAB3GAP2 (77% identical), tropical clawed frog rab3gap2 (71% identical), zebrafish rab3gap2 (57% identical), Drosophila melanogaster Rab3-GAP (27% identical), Caenorhabditis elegans rbg-2 (21% identical).
Diseases named in the same sentence as RAB3GAP2 in open-access papers:
RAB3GAP2 is named in the same sentence as 18 diseases in open-access papers, as found by Europe PMC text mining. Sharing a sentence is not in itself a finding about the gene and the disease. The quoted sentences say what the papers report.
Martsolf syndrome (7 papers, 2012 to 2022). "Some clinical overlap exists between DOORS syndrome and Martsolf syndrome (caused by mutations in RAB3GAP2 gene [OMIM 212720]; shared aspects include seizures, intellectual disability, abnormal toenails, and short phalanges), and other syndromes." (PMID 24291220, 2014). "From the genotype, Martsolf syndrome is more often associated with a mutation in RAB3GAP2." (PMID 36553631, 2022). "44% of Martsolf syndrome cases have mutations in RAB3GAP1 or RAB3GAP2, which perturb but do not completely abolish the expression or function of the encoded protein." (PMID 30856165, 2019). "Loss-of-function mutations in Rab3GAP1 and Rab3GAP2 produce clinically almost indistinguishable conditions, Warburg Micro syndrome and Martsolf syndrome, characterized by brain, eye, and endocrine abnormalities." (PMID 25710274, 2015).
Warburg micro syndrome (7 papers, 2014 to 2024). "RAB18, RAB3GAP1, RAB3GAP2 and TBC1D20 are each mutated in Warburg Micro syndrome, a rare autosomal recessive multisystem disorder." (PMID 26063829, 2015). "RAB3GAP1 and RAB3GAP2 were characterized as forming a complex with GAP activity towards Rab3 isoforms before their involvement in Micro syndrome, or that of RAB18, was known." (PMID 26063829, 2015). "Mutations in RAB18, RAB3GAP1, RAB3GAP2, and TBC1D20 have caused Warburg micro syndrome, a rare autosomal recessive multisystem disorder, suggesting that RAB3GAP1, RAB3GAP2, and TBC1D20 might play roles in PRRSV-2 replication." (PMID 38607975, 2024). "Gene RAB3GAP2 (RAB3 GTPase activating non-catalytic protein subunit 2) was implicated in neurodevelopment and Warburg Micro syndrome, whereas PJA2 (praja ring finger ubiquitin ligase 2) degraded MOB1 to support glioblastoma growth." (PMID 27100869, 2016).
microphthalmia (3 papers, 2012 to 2021). Congenital or developmental anomaly in which the eyeballs are abnormally small. "Mutations in RAB3GAP1 and RAB3GAP2 cause the autosomal recessive Warburg Micro and Martsolf syndromes, which involve congenital cataracts, microphthalmia, postnatal microcephaly and developmental delay." (PMID 22870394, 2012). "No pathogenic variants were identified in any other known microphthalmia-associated loci, specifically RAB3GAP2 and FOXE3, also located on chromosome 1." (PMID 33671840, 2021).
autosomal recessive spastic paraplegia (1 paper, 2022). "Examples include SPG11 (MIM# 610844) associated with autosomal recessive spastic paraplegia, RAB3GAP2 (MIM# 609275) linked to autosomal recessive Marsolf syndrome, and NPHP4 (MIM# 607215) linked to autosomal recessive nephronophthisis." (PMID 35330423, 2022).
cancer (2 papers, 2020 to 2021). A tumor composed of atypical neoplastic, often pleomorphic cells that invade other tissues. "The 3 most frequent DSV genes observed in cancer patients were identified as ADCY9, AURKAPS1, and RAB3GAP2 (p < 0.05)." (PMID 33431054, 2021). "We also identified another genomically co-localized signature, RAB3GAP2, located on 1q41, which has not been detected as a pan-cancer amplicon." (PMID 33057153, 2020).
RAB3GAP2 also shares sentences with these, for which no sentence is quoted: congenital cataracts (2 papers); developmental delay (2); microcephaly (2); bladder cancers (1); cardiac failure (1); cataract (1); demyelinating peripheral neuropathy (1); DOORS syndrome (1); glioblastoma (1); hypogonadotropic hypogonadism (1); Intellectual disability (1); Microcornea (1); Neurological Disorder (1).